RNU6-42P (RNA, U6 small nuclear 42, pseudogene)
Synonyms: RNU6-42
Gene: Small nuclear RNA gene on chromosome 3 (196,784,980 to 196,785,086, reverse strand). Ensembl gene ENSG00000206892.
Homologues: Paralogues in human: RNU6-33P (98% identical), RNU6-1 (97% identical), RNU6-2 (97% identical), RNU6-3P (97% identical), RNU6-4P (97% identical), RNU6-5P (97% identical), RNU6-6P (97% identical), RNU6-9 (97% identical), RNU6-12P (96% identical), RNU6-13P (96% identical), RNU6-17P (96% identical), RNU6-18P (96% identical), and 1286 more.